SMIM15 (small integral membrane protein 15)
Synonyms: C5orf43; DKFZP686E2158
Tractability: Antibody: UniProt predicts a signal peptide or a membrane-spanning region.
Gene: Protein-coding gene on chromosome 5 (61,157,704 to 61,163,142, reverse strand). Ensembl gene ENSG00000188725.
Subcellular location: Membrane
Gene Ontology:
Cellular component: membrane
Genetic constraint (gnomAD): Loss-of-function variants: 5 observed, 7.08 expected, observed/expected ratio (o/e) 0.71, 90% interval 0.37 to 1.46. That is too few expected variants to judge how well the gene tolerates losing a copy. Missense variants: 81 observed, 89.43 expected, observed/expected ratio (o/e) 0.91, 90% interval 0.76 to 1.09. Synonymous variants: 30 observed, 32.83 expected, observed/expected ratio (o/e) 0.91, 90% interval 0.68 to 1.24.
Homologues: Orthologues: macaque SMIM15 (100% identical), mouse Smim15 (99% identical), guinea pig SMIM15 (97% identical), rat Smim15 (97% identical), dog SMIM15 (78% identical).
Diseases named in the same sentence as SMIM15 in open-access papers:
SMIM15 is named in the same sentence as 2 diseases in open-access papers, as found by Europe PMC text mining. Sharing a sentence is not in itself a finding about the gene and the disease.
SMIM15 shares sentences with these, for which no sentence is quoted: Diabetes (1 paper); Obesity (1).